IL10 (interleukin 10)
Diseases named in the same sentence as IL10 in open-access papers (continued):
Sharing a sentence is not in itself a finding about the gene and the disease.
selenium deficiency (4 papers, 2020 to 2025). A nutritional deficiency disease resulting from inadequate selenium levels in the body, which can lead to impaired function of selenoproteins essential for antioxidant defense and thyroid hormone metabolism. "Selenium deficiency increases oxidative stress and increases inflammatory marker expression (iNOS, IL-1β, IL-12, IL10, PTGE, and NF-κB) and reduces the synthesis of antioxidant enzymes (CAT, T-AOC, SOD, and GSH-Px) in macrophages in vitro." (PMID 40681871, 2025). "It has been suggested that selenium deficiency presents with inhibition of selenoproteins and altered secretion of IL‐10, IL‐12p40, and IFN‐γ, leading to Th1/Th2 imbalance by shifting the balance toward Th1 responses." (PMID 33943012, 2021). "As IL-10, IL-13, IL-4, and IL-5 are part of Th2 responses, selenium deficiency may have induced more Th2 responses than Th1 responses in the lungs of mice infected with influenza virus." (PMID 33207753, 2020). "However, mice without Selenof expression may be showing some sensitivity to selenium-deficiency, where IL-10 was detected in lower amounts in Selenof-KO control mice compared to their WT littermates." (PMID 34638991, 2021). "Selenium deficiency decreased the mRNA expression of IFN-γ and IL-2, but increased the mRNA expression of IL-10, IL-13, IL-4, and IL-5 in the mediastinal lymph nodes." (PMID 33207753, 2020).
septic arthritis (4 papers, 2016 to 2025). "Mice deficient in IL-10 developed more severe septic arthritis, characterized by a higher bacterial load in the kidneys compared to the wild-type mouse strains." (PMID 38410388, 2024). "This shows superior therapeutic efficacy of BM-MSC1, in treating septic arthritis in aged murine models, demonstrating excellent anti-inflammatory and regenerative capabilities through significant modulation of markers such as IL-10, VEGF, and TNF-α." (PMID 41296765, 2025). "This suggests a protective role of IL-10 in the context of septic arthritis." (PMID 38410388, 2024). "Thus, increasing CD4+IL-10+T+ cells and IL-10 production at later time points in the course of septic arthritis at which the infection was already controlled could be a mechanism to reduce joint inflammation in ST2−/− mice." (PMID 29867945, 2018).
staphylococcal infection (4 papers, 2011 to 2024). An infection caused by Staphylococcus. "Additionally, the presence of IL-10 has been highly associated with other types of staphylococcal infection." (PMID 30626412, 2019). "An interleukin-10 knockout could also influence staphylococcal infection." (PMID 39019114, 2024). "This could explain why staphylococcal infections often become chronic due to the immunosuppressive activity of IL-10, as compared to infections by gram-negative bacteria where inflammation is more acute and of higher magnitude." (PMID 21857913, 2011).
systemic juvenile idiopathic arthritis (4 papers, 2006 to 2021). "A similar decrease of IL-10 expression has been described in other auto-inflammatory diseases that are known to have increased IL-1β levels, such as systemic juvenile idiopathic arthritis." (PMID 33324407, 2020).
tauopathies (4 papers, 2016 to 2025). "Because Il10 and sIl10R had opposing effects in TgCRND8 mice consistent with the hypothesis that Il10 worsened neuropathology, we wanted to establish the role of Il10/sIl10R signaling pathways in mouse models of tauopathy." (PMID 40055831, 2025). "In addition, the LC exhibited exaggerated expression of pro- and anti-inflammatory mediators (IL-6, TNFα, inducible nitric oxide synthases 2 (iNOS2), and interleukin 10 (IL-10)) in transgenic rats suggesting that tauopathy affects also the immune background in LC." (PMID 26792515, 2016). "Moreover, gene expression of the anti-inflammatory cytokine IL-10 was increased in unstressed transgenic rats as well as in transgenic animals exposed to a single stressor, indicating activation of compensatory immune mechanisms at the level of the LC against a background of tauopathy." (PMID 26792515, 2016).
temporal lobe epilepsy (4 papers, 2015 to 2023). A localization-related (focal) form of epilepsy characterized by recurrent seizures that arise from foci within the temporal lobe, most commonly from its mesial aspect. "Patients with temporal lobe epilepsy have more IL-10 producing cells than control group individuals, and further immune cells show effector T-cells activation with low-grade inflammation." (PMID 32403392, 2020).
Trichinella spiralis infection (4 papers, 2017 to 2025). "This study suggests that S. officinalis possesses strong antifibrotic and anti-inflammatory properties, by downregulating FN1, TNF-α, and TGF-β while maintaining IL-10 expression, making it a valuable adjunct therapy for trichinellosis." (PMID 41026274, 2025). "Their effect on the cytokine profile of INF-γ and IL-10 is promising to reinforce their therapeutic use against trichinellosis." (PMID 28761478, 2017). "The target of albendazole and myrrh on the profile of IFN-γ and IL-10 on these cytokines were encouraging to reinforce their therapeutic use against trichinellosis." (PMID 28761478, 2017). "We aimed to assess the expression of two different cytokines as a representative for inflammatory and anti-inflammatory cytokines (INF-γ and IL-10) in the intestinal tissues of experimental trichinellosis in mice and treated with albendazole (reference drug) or myrrh (plant extract)." (PMID 28761478, 2017). "Improvement of signs of inflammation during experimental trichinellosis is correlated with the increase of regulatory cytokines IL-10, TGF-β and regulatory T cells and down-regulation of pro-inflammatory cytokines; IFN-γ, IL-6, and IL-17; in the spleens, mesenteric lymph nodes and colon of mice." (PMID 28761478, 2017). "Trichinella spiralis infection markedly enhanced the levels of proinflammatory cytokines (TNF-α, IL-6, IL-17, and ICAM-1, P < 0.01) but remarkably reduced the level of anti-inflammatory cytokine (IL-10) in colon, compared with control group (P < 0.01)." (PMID 29662452, 2018).
tuberculoid leprosy (4 papers, 2014 to 2023). A principal or polar form of leprosy in which the skin lesions are few and are sharply demarcated. "Of the 24 soluble mediators of inflammation that were measured, 7 showed significant differences between lepromatous and tuberculoid leprosy (CCL2, CCL17, CCL18, IFNA1, IL10, IL22, and TNF)." (PMID 25412496, 2014). "This supports previous studies which found that the xenophagy inhibiting IL-10 cytokine is predominant in multibacillary leprosy (MB) compared to high levels of IL-26, IFN-γ, and TNF-α (xenophagy-inducing cytokines) found during paucibacillary tuberculoid leprosy (PB)." (PMID 38133338, 2023).
tularemia (4 papers, 2013 to 2021). Tularemia is an infection caused by the bacterium Francisella tularensis. "Further studies are needed to identify the source of IL-10 in the murine lung during respiratory tularemia." (PMID 34202420, 2021). "Many intracellular bacteria, including Francisella tularensis, the agent of tularemia, utilize the anti-inflammatory cytokine IL-10, to evade the host immune response." (PMID 26114641, 2015). "In contrast, production of IL-10 was observed during early- and late-phase tularemia, consistent with our previous observation of rapid establishment of a principally anti-inflammatory environment in the lungs of Ft-infected mice." (PMID 23554897, 2013). "A number of studies have demonstrated that many intracellular pathogens, such as F. tularensis, a Gram-negative intracellular bacterium that causes tularemia, use IL-10 to evade the host immune defense especially in the initial stages of infection." (PMID 26114641, 2015). "Serum levels of eotaxin, G-CSF, IFNα, IFNγ, IL-1β, IL-2, IL-6, IL-8, IL-10, IP-10, MCP-1, MIP-1α, MIP-1β, and PDGF were significantly increased in tularemia patients when compared to healthy controls and/or between different time points of sampling." (PMID 33114188, 2020).
vaginal infection (4 papers, 2020 to 2023). "Murine models of N. gonorrhoeae vaginal infection suggest that host IL-10 production in response to infection plays a role in blunting adaptive immune responses to N. gonorrhoeae bacteria." (PMID 37027389, 2023). "Group M presented that expression levels of IFN-γ, IL-17, IL-6, TGF-β, IL-4, and IL-10 were significantly elevated in vaginal secretions after CA vaginal infection." (PMID 35958550, 2022). "We also found an increased IL-10 among the participants with lesions and vaginal infections." (PMID 37635942, 2023). "Finally, vaginal infection among the participants with CIN expressed immune modulation which favoured immunosuppression with an increased level of IL-10." (PMID 37635942, 2023). "In the presence of vaginal infection, TNF-α decreased among CIN 1+ participants while IL-10 remained elevated." (PMID 37635942, 2023). "The second of these was assessed with a multi-analyte flow assay kit to determine the levels of IL-6, TNF-α, IL-1β, IL-10, IL-1α, IL-17a, MCP-1, and IFN-γ in the supernatant of cervical tissue homogenate of GrpE-immunized mice and control groups after vaginal infection." (PMID 32849509, 2020).
vascular dementia (4 papers, 2019 to 2022). A degenerative vascular disorder affecting the brain. "In our study, IL-10 was also statistically significantly associated with all-cause dementia and vascular dementia even after correction for multiple testing." (PMID 36085081, 2022).
viral meningitis (4 papers, 2015 to 2023). Inflammation of the membranes surrounding the brain and spinal cord due to a viral infection. "Previous studies have found increased levels of inflammatory cytokines and chemokines in the CSF of patients with viral meningitis, such as IL‐6, IL‐1b, TNF‐α, IL‐10, CXC family chemokines and growth factors." (PMID 37904697, 2023).
vitamin A deficiency (4 papers, 2012 to 2020). Deficiency of vitamin A due to malnutrition, malabsorption, or dietary lack. "A mice model has shown that vitamin A deficiency enhances the development of IL-10 Th2 secreting cells and reduces Th1 development." (PMID 25268355, 2014). "Intriguingly, vitamin A deficiency in mice seems to be associated with elevated IL-10 competent Treg cells." (PMID 25268355, 2014). "Both the number of IL-4+ T cells analyzed ex vivo and the SEA-specific IL-4 and IL-10 responses were either unaffected or only slightly reduced by vitamin A deficiency." (PMID 22927819, 2012). "Vitamin A deficiency at the time of exposure to antigen may increase the development of interleukin 10 (IL-10) producing Th2 and regulatory cells, and decrease the development of Th1 memory cells." (PMID 32309235, 2020). "Taken together, these results indicate that during vitamin A deficiency Treg cells may be important subsets in IL-10 production." (PMID 25268355, 2014). "Their results indicate that proper vitamin A supplementation was associated with an increase in IL-10 concentration and/or decrease in TNF-α, while vitamin A deficiency was associated with the opposite results." (PMID 28730424, 2018).
X-linked lymphoproliferative disease (4 papers, 2008 to 2025). X-linked lymphoproliferative disease is a hereditary immunodeficiency characterized, in the majority of cases, by an inadequate immune response to infection with the Epstein-Barr virus (EBV). "The IL-6, IL-10, and IFN-γ levels and the ratios of IL-10 to IFN-γ were different among EBV-HLH, other infection-associated HLH, malignancy-associated HLH, familial HLH, and X-linked lymphoproliferative disease." (PMID 35296096, 2022). "In fact, lack of IL-10 production by CD4+ T helper cells in X-linked lymphoproliferative disease (XLP) patients impaired the development of B cell responses." (PMID 27463374, 2016). "Furthermore, IL10 production by T cells is deficient in human ICOS deficiency, X-linked lymphoproliferative disease and in subsets of CVID patients, further underscoring the potential involvement of IL10 in the pathogenesis of hypogammaglobulinemia." (PMID 18254984, 2008). "For example, patients with X-linked lymphoproliferative disease (XLP) and STAT1 gain-of-function mutation presented low levels of IL-10 and IFN-γ." (PMID 35296096, 2022).
adenoid hypertrophy (3 papers, 2022 to 2026). "Further study is needed to evaluate the IL-10 rs1800896 polymorphism as a prognostic value for adenoid hypertrophy." (PMID 35207552, 2022). "Limited and preliminary work was done to assess the role of IL-10-genetic polymorphism and HHV6, CMV, and Epstein–Barr virus infection in adenoid hypertrophy in children." (PMID 35207552, 2022). "Regarding IL-10 rs1800896, the GG genotype may confer resistance against adenoid hypertrophy and restrict adenoid tissue growth." (PMID 40061126, 2025). "Moreover, increasing levels of proinflammatory cytokines, including IL-10, were found in children with chronic tonsillitis and adenoid hypertrophy." (PMID 35207552, 2022).
Aortic dissection (3 papers, 2025). Aortic dissection refers to a tear in the intimal layer of the aorta causing a separation between the intima and the medial layers of the aorta. "Within 2 h after the formation of aortic dissection, plasma endotoxin and cytokine levels including TNF-α, IL-6, and interleukin-10 (IL-10) showed significant elevation, progressing to peak concentrations by 6 h." (PMID 41357087, 2025).
asbestosis (3 papers, 2018 to 2025). A lung disorder caused by inhalation of asbestos fibers. "Lung macrophages isolated from humans with asbestosis showed a significant induction in TGFB1, IL10, ARG1, and MRC1 gene expression compared with healthy humans." (PMID 40208691, 2025).
basal cell carcinoma (3 papers, 2011 to 2025). A carcinoma involving the basal cells. "CD4+CD25+Foxp3+ T-cells can be found intermingled with human basal cell carcinoma along with the TH2 cytokines IL-4 and IL-10." (PMID 34771569, 2021).
breast fibroadenoma (3 papers, 2022 to 2025). "In patients with BC and fibroadenomas, the levels of IL-1β (p = 0.0123), IL-4 (p = 0.0001), and IL-10 (p = 0.0000) were significantly higher than the norm and statistically significantly different from the control values." (PMID 40429927, 2025).
carditis (3 papers, 2014 to 2025). "Hypo-activation of host response to infection can lead to increased bacterial burden and increased carditis in the Mir155-/- mouse, and hyper-activation of both innate and adaptive responses can lead to excess inflammation and carditis in Il10-/- and DKO mice." (PMID 26252010, 2015). "We also showed that both miR-155 and IL-10 are important for protection against heart inflammation and carditis, and that LA development and Th1 responses are predominantly mediated by miR-155-independent effects of IL-10." (PMID 26252010, 2015). "The established involvement of IL-10 in the murine model of Borrelia burgdorferi-induced Lyme arthritis and carditis allowed us to assess the interplay between IL-10 and miR-155 in vivo." (PMID 26252010, 2015). "In contrast, while Il10-/- and DKO mice also developed severe carditis, hearts had reduced bacterial numbers and elevated Th1 and innate cytokine expression." (PMID 26252010, 2015).
cholangitis (3 papers, 2014 to 2024). An acute or chronic inflammatory process affecting the biliary tract. "Zen research showed that the expression of Th2 cytokines (IL-4, IL-5, and IL-13) and regulatory cytokines (IL-10 and transforming growth factor-β) was upregulated in the lesion tissues of patients with IgG4-related sclerosing pancreatitis and cholangitis." (PMID 38669380, 2024). "Serum IL-10 was elevated in IgG4-related pancreatitis, cholangitis, or tubulointerstitial nephritis, supporting that IL-10 might participate in the sIgG4 elevation and IgG4-positive plasma cell infiltration in IgG4-RD." (PMID 25548435, 2014). "To address the hypothesis that MMTV plays a role in the development of inflammation in the IL-10−/− mouse model, we employed a cART regimen previously shown to ameliorate MMTV cholangitis in the NOD.c3c4 autoimmune biliary disease model of primary biliary cholangitis." (PMID 36869359, 2023).
chronic endometritis (3 papers, 2019 to 2021). A non-granulomatous or granulomatous chronic inflammation of the endometrium. "Likewise, IL-10 has also been suggested to play a role in spontaneous chronic endometritis in mares." (PMID 34944269, 2021).
clear cell renal cell carcinoma (3 papers, 2006 to 2022). "In addition, IL10 is an important immune regulatory cytokine in TME, and a recent study has shown that IL10 promotes cancer cell metastasis and proliferation via immunosuppression, and also has a predictive value in clear cell renal cell carcinoma." (PMID 36146599, 2022).
complex regional pain syndrome (3 papers, 2019 to 2023). A chronic pain syndrome characterized by a disproportionate spontaneous or stimulus-induced pain, accompanied by a variably mixed myriad of autonomic and motor disorders including symptoms such as swelling, allodynia, skin blood supply and trophic disturbances. "Previous studies showed that intrathecal administration of recombinant IL-10 was anti-allodynic by modulating microglial activation in the mouse model of acute stage of complex regional pain syndrome." (PMID 33841075, 2021). "The serum level of anti-inflammatory cytokine such as IL-10 was lower in patients with complex regional pain syndrome (CRPS) than in the controls." (PMID 30755780, 2019).
coronary stenosis (3 papers, 2021 to 2024). Narrowing of the coronary artery lumen diameter. "In the present study, an increase in IL-10 baseline levels has been linked with an increased risk of suffering future cardiovascular events in a 10-year follow-up (p = 0.047; HR = 1.3) in a cohort of patients with angiographically proven coronary stenosis." (PMID 39199367, 2024). "Interestingly, our results revealed increased levels of IL-10 in a group of patients with more severe functional (p = 0.011) and anatomical (p = 0.016) coronary stenosis, and even elevated IL-10 levels were somewhat predictive of significant functional and anatomical coronary lesions." (PMID 34660716, 2021). "The study revealed that a combination of IL-6, IL-10, and CD4 + T lymphocytes outperformed individual biomarkers in predicting functional coronary artery stenosis." (PMID 38443781, 2024). "Furthermore, the combination of IL-6, IL-10, and CD4+ T lymphocytes is a better predictor of functional coronary stenosis than any single biomarker." (PMID 34660716, 2021).
Cryptococcal meningitis (3 papers, 2016 to 2025). Meningeal inflammation produced by cryptococcus neoformans, an encapsulated yeast that tends to infect individuals with acquired immunodeficiency syndrome and other immunocompromised states. "Other variables including peripheral white blood cells, PD-L1, CXCL10, CCL11, IFN-γ, IL-2 and IL-10 did not independently predict the levels of CSF leukocytes count with cryptococcal meningitis." (PMID 39928682, 2025).
disseminated candidiasis (3 papers, 2016 to 2021). Systemic candidiasis occurs when Candida yeast enters the bloodstream and may spread (becoming disseminated candidiasis) to other organs, including the central nervous system, kidneys, liver, bones, muscles, joints, spleen, or eyes. "The reduced virulence of the ISW2 null mutant DRL6 in a mouse model of disseminated candidiasis was associated at day 2 PI with decreased up-regulation of IL-6, TNF-α, MIP1-α, and IL-10, cytokines and chemokines that are known to play a role in innate host defense against Candida in vivo." (PMID 27727302, 2016). "A similar role of TLR2 was also observed in a murine model of disseminated candidiasis, where TLR2 exerts anti-inflammatory effect by promoting IL-10 production and Treg cell proliferation." (PMID 34912336, 2021).